CKAP4 (cytoskeleton associated protein 4)
Diseases named in the same sentence as CKAP4 in open-access papers (continued):
Sharing a sentence is not in itself a finding about the gene and the disease.
cancer (continued). "In this study, we identify a crucial mechanical sensor, termed CKAP4, underpinning solid stress-induced cancer malignancy." (PMID 39528501, 2024). "Altogether, our data suggested that solid stress-promoted cancer metastasis by inducing microtubule branching, during which CKAP4 condensation played an important role." (PMID 39528501, 2024). "Cytoskeleton-associated protein 4 (CKAP4), or CLIMP63, mediates a variety of cancer signaling pathways." (PMID 39528501, 2024). "CKAP4 is secreted into the serum by tumors and is expected to be a novel serological marker for the diagnosis of various cancers." (PMID 39281688, 2024). "Our data showed that CKAP4 in cancer cells started to condense in response to solid stress, and solid stress from 2 to 6 pieces of coverslips provided the best effects without obvious cell damage." (PMID 39528501, 2024). "In this study, we reported the crucial role of oncoprotein CKAP4 in bridging solid stress and cancer malignancy by LLPS." (PMID 39528501, 2024). "Altogether, the calcium ion-dependent CKAP4 phase separation denotes a special mechanism for cancer cells to sense solid stress from within cells, which proves to be an important missing block in cancer biomechanics." (PMID 39528501, 2024). "Cytoskeleton-associated protein 4 (CKAP4) binds to the DKK-1 and p85α subunit of PI3K to activate PI3K/AKT signal pathway to stimulate cancer cell proliferation." (PMID 36805679, 2023). "Cytoskeleton-associated protein 4 (CKAP4) is a novel DKK1 receptor that binds to DKK1 to activate AKT signaling and enhance cancer cell proliferation." (PMID 35712490, 2022). "It has been reported that CKAP4 is a protumor molecule to promote progression of various cancers, such as pancreatic, lung, esophageal, and renal tumors." (PMID 33614703, 2020). "Sufficient studies have confirmed that CKAP4 correlated with various cancers’ progress and prognosis." (PMID 33614703, 2020). "Another report considered CKAP4 as a promotion protein on cancer progression through CCNB signaling in ccRCC." (PMID 33614703, 2020). "Kimura and coworkers found that CKAP4 protein can be secreted with small extracellular vesicles (SEVs) and reflect cell surface expression of CKAP4 in cancer cells." (PMID 33614703, 2020). "Previous study has demonstrated that CKAP4-mediated DKK1 signaling regulated cancer cell growth via PI3K/AKT pathway." (PMID 32587255, 2020). "The prognosis was the best when carcinoma cells presented high amount of CKAP4 and high expression level of DHHC2." (PMID 33614703, 2020). "The results showed that the expression of CKAP4 in HCC tumor tissues was significantly higher than that in para-carcinoma normal tissues." (PMID 33614703, 2020). "Of these substrates, CKAP4, CD9, and CD151 have been associated with initiation and progression of cancer." (PMID 24995331, 2014). "The discovery that CKAP4/p63, the receptor for APF, is a substrate of ZDHHC2, provides an important link between the proliferative properties of many types of cancer cells and the reduced expression or mutation of ZDHHC2." (PMID 23457560, 2013). "Furthermore, CKAP4 seems to enhance cancer cell migration by binding to β1 integrin and negatively regulating α5β1 integrin’s recycling." (PMID 41149482, 2025). "However, recent preclinical and clinical studies have revealed that the interaction of DKK1 and CKAP4 on the cell membrane activates the Akt signaling pathway, wherein various types of cancers predominantly rely on cell proliferation." (PMID 40282454, 2025). "Additionally, the synchronous expression of both DKK1 and CKAP4 seems to result in a worse prognosis in different types of cancer." (PMID 39795613, 2025). "Targeting a molecule like CKAP4, which is involved in cancer progression, could offer effective alternative therapeutic options." (PMID 41149482, 2025). "In addition, targeting CKAP4 can reduce Akt activation and cancer proliferation in gemcitabine-resistant PDAC cells." (PMID 41149482, 2025).
cancer (continued). "Furthermore, CDC42BPB, CKAP4, KMT2D, and PBX2 have been shown to be strongly associated with the development of certain cancers." (PMID 40608007, 2025). "Although CKAP4’s role in disease is often associated with cancer (with conflicting reports on whether it should be considered a cancer suppressor or a cancer promoter molecule), CKAP4 has recently been connected to vascular calcification in CKD." (PMID 40493405, 2025). "In summary, our study bridges the gap between solid stress and cancer metastasis by CKAP4 phase separation-mediated microtubule branching, and the discovery of a CKAP4-based intracellular sensor for solid stress in tumors provides a new insight into the biomechanics to drive cancer progression." (PMID 39528501, 2024). "Taken together, cell compaction is a typical physical trait in cancer progression, and CKAP4 may potentially bridge cell compaction and solid tumor metastasis." (PMID 39528501, 2024). "Thus, the magnitude of force and elasticity of applied material are necessary to induce CKAP4 condensation in cancer cells, highlighting the dominant role of solid stress in driving CKAP4 condensation." (PMID 39528501, 2024). "These micron-scaled CKAP4 puncta adhere tightly onto microtubules and dramatically reorchestrate their curvature and branching to enhance cell spreading, which, as a result, boosts cancer cell motility and facilitates distant metastasis in vivo." (PMID 39528501, 2024). "DKK1/CKAP4 signaling through PI3K/AKT pathway to promote cancer cell proliferation." (PMID 39107271, 2024). "Moreover, both endogenously- and exogenously-expressed CKAP4 showed consistent condensation across a broad subset of cancer cell lines." (PMID 39528501, 2024). "CKAP4 promotes cancer cell proliferation through the PI3K/AKT pathway." (PMID 39165641, 2024). "In this case, CKAP4 serves as a specific intracellular mechanosensor for solid stress, which may suggest an unprecedented paradigm of how solid stress is sensed by cancer cells." (PMID 39528501, 2024). "In adjacent normal tissues, cells harbored dispersed CKAP4, but in tumor sites of great compaction CKAP4 was shown as speckles, and in metastatic cases (TM+), cancer cells exhibited more evident and denser CKAP4 speckles, in line with the observation of CKAP4 speckles in the cell lines." (PMID 39528501, 2024). "Furthermore, DKK1 and LRP6 can form a ternary complex with cytoskeleton-associated protein 4 (CKAP4), a cell surface receptor that activates PI3K/AKT signaling, to enhance DKK1-dependent cancer cell proliferation." (PMID 37759431, 2023). "Furthermore, their influence extends to the Notch, Wnt, and CKAP4 signaling pathways, crucial pathways involved in cancer development and progression due to their role in cell proliferation, differentiation, and survival." (PMID 37648722, 2023). "Intriguingly, the presence of LRP6 does not compete with CKAP4 for binding with DKK1 owing to the different locations of the binding domain; instead, it enhances DKK1-CKAP4 signaling, thereby promoting cancer cell proliferation more than DKK1-CKAP4 interaction alone." (PMID 35355709, 2022). "We have recently shown that DKK1 promotes cancer progression through CKAP4 (DKK1-CKAP4 signaling)." (PMID 34117362, 2021). "It has been recently shown that CKAP4 targeting therapy via monoclonal antibody may be a novel therapeutic strategy for various cancers in which the DKK1-CKAP4 signaling axis is activated." (PMID 34117362, 2021). "Relationship between CKAP4 protein expression and various cancers prognosis." (PMID 33614703, 2020). "From the present studies, we can speculate that CKAP4 can combine with its ligand to affect cancer growth." (PMID 33614703, 2020). "Thus, the combination of anti-DKK1/CKAP4 and anti-PD-1 treatment may have promising results in anti-cancer treatment." (PMID 41149482, 2025).
cancer (continued). "Therefore, deciphering the gene status, expression regulation, functions of CKAP4 in different diseases may shed new light on CKAP4-based cancer diagnosis and therapeutic strategy." (PMID 33614703, 2020). "The interaction between DKK1 and CKAP4 activates the PI3K/AKT signaling pathway, promoting cancer cell proliferation." (PMID 41149482, 2025). "Moreover, the potential efficacy of anti-CKAP4 treatments, particularly in combination with existing therapies, their capacity to overcome drug resistance in certain cancer types, and their possible immunomodulatory effects, could offer significant advantages in clinical settings." (PMID 41149482, 2025). "Thus, either DKK1 or CKAP4 could serve as molecular targets for anti-cancer therapy." (PMID 39795613, 2025). "CKAP4-targeted aptamers present dual-action blocking of CKAP’s interaction with DKK1 and, thus, disrupting PIK/Akt signaling as well as impeding cancer cell adhesion and migration by decreasing internalization and recycling of α5β1 integrin." (PMID 41149482, 2025). "After examining the pulled‐down proteins by lncRNA ARHGAP5‐AS1 using mass spectrometry proteomics, we identified multiple cancer‐related proteins including CSDE1, ZC3HAV1, CCT8, CKAP4, PARP1, PEG10 and APEX1 in HepG2." (PMID 36354136, 2022). "Collectively, these data provided evidence that GOLPH3 interacts with CKAP4 to enhance the secretion of exosomal WNT3A, thereby inducing metastasis and the cancer stem cell-like phenotype in NSCLC." (PMID 34671013, 2021). "It has been demonstrated that DKK1 binds to cytoskeleton-associated protein 4 (CKAP4) with high affinity, leading to the activation of Akt by forming a complex between CKAP4 and PI3K, resulting in the proliferation of normal cells and cancer cells." (PMID 33613114, 2021). "In conclusion, our results indicate that GOLPH3 enhances the secretion of exosomes containing CKAP4 and WNT3A, which activate the WNT/β-catenin pathway, thereby contributing to metastasis and the cancer stem cell-like phenotype in NSCLC." (PMID 34671013, 2021). "Notably, CKAP4 interaction with oncogenic ligands, such as DKK1, regulates signaling pathways involved in cancer." (PMID 41149482, 2025). "Nonetheless, in cancer cells expressing CKAP4 but not DKK1 the anti-CKAP4 antibody did not exhibit such efficiency." (PMID 41149482, 2025). "Although it has not been studied in the serum of patients with EAC, CKAP4 is also secreted into the serum and has been found elevated in various types of cancer." (PMID 39795613, 2025). "Although plentiful researches focused on the relationship between CKAP4 and cancer, there were also studies that showed that CKAP4 played an important role in noncancers." (PMID 33614703, 2020). "Therefore, FOXM1 may be a molecular target which present a synergistic clinical effect for cancers which express it as well as DKK1 and CKAP4." (PMID 34117362, 2021). "In addition, CKAP4 translocated to the nucleus of T24 cells and regulated the CCN2 expression after APF treatment (CCN2 overexpression inhibits invasion and metastasis of the cancer cells both in vitro and in vivo)." (PMID 33614703, 2020). "However, these anti-tumor results were evident in cancer cells expressing both DKK1 and CKAP4 and not only CKAP4, or neither DKK1 nor CKAP4." (PMID 41149482, 2025). "For the individuals studied here, increased levels of CKAP4 may not be driving disease, but the finding opens a potential line of anti-CKAP4 antibody drug development for SLE patients; an avenue previously only promoted for cancer treatment." (PMID 35523803, 2022).
tumor (38 papers, 2013 to 2026). "Comparative analysis of AEBP1 (ACLP) expression with CKAP4 expression in human tumor samples will be necessary to elucidate the receptor-ligand axis underlying CAF-mediated tumor remodeling and immune regulation." (PMID 41373631, 2025). "CKAP4 expression was observed in the tumor cytoplasm and nucleus and was significantly associated with MIBC and LN metastasis." (PMID 40282454, 2025). "The review highlights new findings on CKAP4′s involvement in tumor progression, its potential as a diagnostic biomarker, and its promise as a therapeutic target." (PMID 41149482, 2025). "The expression CKAP4 in tumor cells and CAFs was significantly associated with an aggressive BCa phenotype." (PMID 40282454, 2025). "We observed varying levels of CKAP4 expression in CAFs within the tumor stroma, which were significantly associated with more aggressive clinicopathological features." (PMID 40282454, 2025). "Next, to explore the role of cell compaction in driving tumor metastasis, we focused on a newly identified mechanically associated protein, CKAP4, which was discovered in one of our previous studies." (PMID 39528501, 2024). "The interaction between DKK1 and cytoskeleton-associated protein 4 (CKAP4) offers a window into a deeper understanding of tumor biology and the development of new therapeutic strategies." (PMID 37835450, 2023). "It suggests that the mutation of CKAP4 could be used to treat excessive proliferation diseases such as tumor." (PMID 33614703, 2020). "Whether the palmitoylation site of CKAP4 is mutated in tumor tissues and the expression change of DHHC2 in other tumors require further investigation." (PMID 33614703, 2020). "However, DKK1 binding to its receptor cytoskeleton associated protein 4 (CKAP4) promoted tumor progression." (PMID 31167446, 2019). "It has been shown that binding of DKK1 to CKAP4 leads to cell proliferation, while anti-CKAP4 antibodies seem to have anti-tumor activity." (PMID 39795613, 2025). "Targeting DKK1 or CKAP4 results in increased accumulation of cytotoxic T-cells in tumor lesions as well as improved ability of the macrophages to activate cytotoxic lymphocytes." (PMID 41149482, 2025). "In tumor tissues, CKAP4 was observed in the cytoplasm of tumor cells and CAFs at various degrees and intensities." (PMID 40282454, 2025). "At the same time, higher serum CKAP4 is correlated with worse pathological stage, histological grade, and bigger tumor diameter." (PMID 41149482, 2025). "The findings of this study indicate that CKAP4 expression in tumors has potential as a novel biomarker for predicting tumor aggressiveness and poor prognosis in cases of BCa." (PMID 40282454, 2025). "Apart from the various biological processes in which CKAP4 is involved, it also acts as a pro-tumor molecule." (PMID 39795613, 2025). "Pharmacological treatment with a rabbit anti-CKAP4 polyclonal antibody suppressed tumor formation in mice, indicating the potential of CKAP4 as another antitumor target linked to this pathway." (PMID 40394415, 2025). "In their study, it was determined that DKK1 supports cell proliferation by binding to CKAP4, and blocking this axis inhibited tumor growth." (PMID 40922300, 2025). "Second, the multivariate analysis adjusted for clinicopathological features revealed that CKAP4 expression in tumor cells was an independent prognostic factor for poor RFS, whereas CKAP4 expression in CAFs did not have a prognostic impact." (PMID 40282454, 2025). "In this study, to investigate their associations with clinicopathological features and patient outcomes, CKAP4 expressed in tumor cells was defined as CKAP4-1, while CKAP4 expressed in CAFs was defined as CKAP4-2." (PMID 40282454, 2025). "First, positive CKAP4 expression was associated with more aggressive pathological features, such as advanced pT stage and presence of LVI in tumor cells, and advanced pT stage, tumor grade 3, presence of LVI, and LN metastasis in CAFs." (PMID 40282454, 2025).
tumor (continued). "In fact, although DKK3 is mainly known as a tumor suppressor, it also binds to CKAP4 through CRD1, acting as an oncogene." (PMID 39795613, 2025). "In the context of HCC, CKAP4 expression has been significantly elevated in HCC tumor tissues compared to adjacent normal liver tissues." (PMID 41149482, 2025). "Knockdown of DKK1 or CKAP4 inhibited cell proliferation, and the anti-CKAP4 antibody seems to suppress tumor formation." (PMID 39795613, 2025). "The anti-CKAP4 antibodies amplify PDAC tumor growth inhibition when used in combination with standard chemotherapy regimens, such as gemcitabine and nab-paclitaxel, in vitro and in murine models." (PMID 41149482, 2025). "The development of humanized anti-CKAP4 antibodies has shown effectiveness in suppressing tumor formation in murine models, offering a new therapeutic avenue." (PMID 41149482, 2025). "In CRC, CKAP4 is also involved in angiogenesis enhancing tumor metastasis both in vitro and in vivo." (PMID 41149482, 2025). "Overexpression of CKAP4 has also been shown to inhibit cell proliferation, colony formation, and tumor growth in xenograft models, whereas CKAP4 knockdown enhanced these processes." (PMID 41149482, 2025). "Intriguingly, CKAP4, as a sensitive intracellular mechanosensor, responds specifically to solid stress in a subset of studied tumor micro-environmental elements through liquid–liquid phase separation." (PMID 39528501, 2024). "The expression of DKK1 and CKAP4 is essential for tumor formation in vivo, suggesting that CKAP4 is a potential molecular target for HCC therapy." (PMID 37835450, 2023). "Gross pathological examination showed that the size of the tumor mass was about 14 × 10 × 6 cm.Mutations were observed in ENPEP (4q25), ZCCHC11, RREB1 (6p24.3), CKAP4 (12q23.3), and other genes were detected by whole exome sequencing." (PMID 36805679, 2023). "It was reported that CKAP4 was minimally expressed in non-tumor cells, therefore, it was adopted as a biomarker for investigation of KB-C2 and KB-C2-k.o.cdk6 metastasis in the tissues of nude mice." (PMID 35459184, 2022). "Anti-CKAP4 antibodies that inhibit the binding of Dkk-3 to CKAP4 reduce tumor formation induced by ESCC cells in xenograft assays." (PMID 36497305, 2022). "The Dkk1-CKAP4 signalling axis can drive cell proliferation and Dkk1 as well as CKAP4 are upregulated in tumours." (PMID 35279766, 2022). "The pharmacological treatment with an anti-CKAP4 antibody suppressed tumor formation in mice, indicating the potential of CKAP4 as an anti-tumor target." (PMID 35355709, 2022). "Nine tumor-bearing mice were divided into three groups (Si QD micelles-CKAP4 injection group, Si QD micelles injection group, and saline injection group)." (PMID 34331597, 2021). "In this study, tumor-bearing mice (n = 12) were intravenously injected with saline (200 μL), Si QD micelles (Si: 4 mg/kg, 200 μL), or Si QD micelles-CKAP4 (Si: 4 mg/kg, 200 μL) and then euthanized 24 h later." (PMID 34331597, 2021). "After tumor formation, A549 tumor tissues and normal lung tissues were collected and incubated with Si QD micelles and Si QD micelles-CKAP4 at 37 °C for 2 h." (PMID 34331597, 2021). "The authors propose using an AKT inhibitor in concert with a CKAP4 inhibitor to target tumor cells and their EVs." (PMID 34207163, 2021). "Effectively inhibiting CKAP4 using a monoclonal antibody showed reduced tumor formation and improved survival in mice models." (PMID 34207163, 2021). "From the initial studies of its molecular structure to the gradual recognition of its biological properties and functions, more and more researches have shown that CKAP4 has a relationship with various types of tumor." (PMID 33614703, 2020). "In this study, we have provided evidence for RBP1 as a biomarker in OSCC, and its novel role as an inducer of autophagy that further promotes in vitro and in vivo tumor cell growth via interaction with CKAP4." (PMID 32587255, 2020).